ZCCHC3 (zinc finger CCHC-type containing 3)
Description:
Nucleic acid-binding protein involved in innate immune response to DNA and RNA viruses. Binds DNA and RNA in the cytoplasm and acts by promoting recognition of viral nucleic acids by virus sensors, such as RIGI, IFIH1/MDA5 and CGAS. Acts as a co-sensor for recognition of double-stranded DNA (dsDNA) by cGAS in the cytoplasm, thereby playing a role in innate immune response to cytosolic dsDNA and DNA virus. Binds dsDNA and probably acts by promoting sensing of dsDNA by CGAS, leading to enhance CGAS oligomerization and activation. Promotes sensing of viral RNA by RIGI-like receptors proteins RIGI and IFIH1/MDA5 via two mechanisms: binds double-stranded RNA (dsRNA), enhancing the binding of RIGI and IFIH1/MDA5 to dsRNA and promotes 'Lys-63'-linked ubiquitination and subsequent activation of RIGI and IFIH1/MDA5.
Synonyms: C20orf99; dJ1103G7.7
Tractability: PROTAC: ubiquitination databases record sites on it; its protein half-life has been measured.
Gene: Protein-coding gene on chromosome 20 (297,570 to 300,321, forward strand). Ensembl gene ENSG00000247315.
Subcellular location: Cytoplasm
Subcellular location (Human Protein Atlas): Vesicles
Gene Ontology:
Molecular function: double-stranded DNA binding; protein binding; RNA binding; nucleic acid binding; zinc ion binding
Biological process: activation of innate immune response; cellular response to exogenous dsRNA; detection of virus; positive regulation of RIG-I signaling pathway; defense response to virus; positive regulation of type I interferon production
Cellular component: cytoplasm
Genetic constraint (gnomAD): Loss-of-function variants: 11 observed, 5.79 expected, observed/expected ratio (o/e) 1.9, 90% interval 1.07 to 1.96. That is too few expected variants to judge how well the gene tolerates losing a copy. Missense variants: 379 observed, 239.96 expected, observed/expected ratio (o/e) 1.58, 90% interval 1.45 to 1.72. Synonymous variants: 193 observed, 116.64 expected, observed/expected ratio (o/e) 1.65, 90% interval 1.47 to 1.86.
Homologues: Orthologues: chimpanzee ZCCHC3 (99% identical), macaque ZCCHC3 (98% identical), dog ZCCHC3 (95% identical), pig ZCCHC3 (93% identical), mouse Zcchc3 (87% identical), rat Zcchc3 (86% identical), guinea pig ZCCHC3 (85% identical).
Diseases named in the same sentence as ZCCHC3 in open-access papers:
ZCCHC3 is named in the same sentence as 8 diseases in open-access papers, as found by Europe PMC text mining. Sharing a sentence is not in itself a finding about the gene and the disease. The quoted sentences say what the papers report.
osteosarcoma (2 papers, 2021 to 2023). A usually aggressive malignant bone-forming mesenchymal neoplasm, predominantly affecting adolescents and young adults. "Using IF and antibody labeling, we observed both endogenous and epitope tagged ZCCHC3 to be evenly distributed without distinct granulation predominantly in the cytoplasm of unstressed cells of multiple lines, including human embryonal carcinoma 2102Ep and osteosarcoma U2OS cells." (PMID 37405998, 2023).
viral infection (2 papers, 2018 to 2023). "Based on our results, we conclude that viral infection induces the association of ZCCHC3 and cGAS, which have a high affinity to viral dsDNA, leading to cGAS activation and induction of downstream effector genes." (PMID 30135424, 2018). "ZCCHC3 directly binds to dsDNA, enhances the binding of cGAS to dsDNA, and is important for cGAS activation following viral infection." (PMID 30135424, 2018). "Here, the authors identify a zinc finger protein, ZCCHC3, that enhances the binding of cGAS to dsDNA and is important for its activation following viral infection." (PMID 30135424, 2018). "The results indicated that the amounts of HSV-1 genomic copy numbers and viral titers in the brains were much higher in Zcchc3−/− than Zcchc3+/+ mice at 6 days after viral infection." (PMID 30135424, 2018). "We next determined the importance of ZCCHC3 in host defense against viral infection in vivo." (PMID 30135424, 2018). "Taken together, these results suggest that ZCCHC3 targets cGAS after viral infection." (PMID 30135424, 2018). "Indeed, we discovered an association between ZCCHC3 and the better-characterized interferon-stimulated gene products MOV10 and ZAP, host proteins known to restrict viral infection in mammals and previously shown by ourselves and others to potently inhibit cell culture retrotransposition." (PMID 37405998, 2023). "In this work we also draw connections between ZCCHC3 and the RNA helicase MOV10 and zinc-finger protein ZAP, host proteins known to restrict viral infection in mammals and previously shown by ourselves and others to potently inhibit human retrotransposition." (PMID 37405998, 2023). "Transcription of cGas but not Zcchc3 was induced by viral infection or IFN-β stimulation in murine lung fibroblasts (MLFs)." (PMID 30135424, 2018).
thyroid cancer (1 paper, 2023). "We also verified the differential expression of ZCCHC gene family genes in commonly used cell lines for thyroid cancer, and all genes were differentially expressed except ZCCHC3 and ZCCHC18." (PMID 37848968, 2023).
viral encephalitis (1 paper, 2018). Encephalitis resulting from viral infection. "Given that HSV-1 is a neurotropic virus and the leading cause of sporadic viral encephalitis, we intra-nasally infected Zcchc3+/+ and Zcchc3−/− mice with HSV-1 and examined HSV-1 genomic copy numbers and viral titers in the brains." (PMID 30135424, 2018).
infection (3 papers, 2018 to 2024). The state of being infected such as from the introduction of a foreign agent such as serum, vaccine, antigenic substance or organism. "Zcchc3−/− mice were more susceptible to lethal infection by DNA viruses." (PMID 30135424, 2018). "The serum cytokines such as IFN-β, CXCL10, and IL-6 induced by infection of HSV-1, VACV, and MCMV were impaired in Zcchc3−/− in comparison to Zcchc3+/+ mice, and ZCCHC3-deficiency renders the mice more susceptible to HSV-1- or VACV-induced death." (PMID 30135424, 2018). "Notably, ZCCHC3 also suppressed the infection of other retroviruses, such as SIV from rhesus macaques (SIVmac), feline immunodeficiency virus (FIV), equine infectious anemia virus (EIAV), and murine leukemia virus (MLV), suggesting that ZCCHC3 inhibits the infection of a broad range of retroviruses." (PMID 38384847, 2024). "By using IF/FISH (fluorescence in situ hybridization) methods, we showed co-localization of HA-tagged ZCCHC3, LSM14A, and the HIV-1 lentivirus gRNA in HeLa CD4+ cells 30 min after infection." (PMID 38384847, 2024). "We found that induction of serum cytokines including IFN-β, CXCL10, and IL-6 following infection of the DNA viruses HSV-1, VACV, and MCMV was severely impaired in Zcchc3−/− in comparison to Zcchc3+/+ mice." (PMID 30135424, 2018). "qPCR analysis indicated that transcription of downstream genes including Ifnb1, Cxcl10, and Il6 following infection with HSV-1 and VACV was markedly inhibited in Zcchc3−/− mouse bone marrow-derived macrophages (BMDMs) and dendrite cells (BMDCs)." (PMID 30135424, 2018). "As ZCCCH3 was reported to positively regulate virus-triggered IFN production, we first investigated whether ZCCHC3 also plays a role in the LINE-1-induced IFN pathway, which was believed to contribute to the auto-immune response under the circumstance of non-infection of the exogenous virus." (PMID 36274734, 2022).
cancer (2 papers, 2017 to 2023). A tumor composed of atypical neoplastic, often pleomorphic cells that invade other tissues. "Others that have been indirectly linked to cancer include HIST1H2AD, two zinc finger proteins (ZCCHC3, ZNF552), and CSRP2, CREBL2, and SERTAD3." (PMID 29282095, 2017).
ZCCHC3 also shares sentences with these, for which no sentence is quoted: embryonal carcinoma (1 paper); HIV-1 infection (1).